IL6 (interleukin 6)
Diseases named in the same sentence as IL6 in open-access papers (continued):
Sharing a sentence is not in itself a finding about the gene and the disease.
endothelial dysfunction (continued). "Serum magnesium related inversely to prevalent AF, lung function (FEV1) and markers of inflammation (IL-6), endothelial dysfunction (vWF) and cardiac dysfunction (cTnT, NT-proBNP), all markers of pathways involved in the pathogenesis of HF." (PMID 29663176, 2018). "Key markers of inflammation (interleukin-6, and hepcidin) and endothelial dysfunction (soluble vascular endothelial cadherin) were also determined in plasma samples." (PMID 30456212, 2018). "Rabbits with experimentally induced hypercholesterolemia presented with elevated levels of TNF-α, IL-6, IL-1, and selected endothelial dysfunction markers, as it was seen in a rat model." (PMID 29713239, 2018). "In this context, nmMLCK inhibition, with two inhibitors acting through two different mechanisms, prevents IL-6 secretion downstream of p65-NFκB activation, the increase of transendothelial migration and the endothelial dysfunction in aortas induced by IH." (PMID 29057883, 2017). "Elevated plasma CRP, TNF-α and IL-6 levels can induce endothelial dysfunction by enhancing free radical generation and simultaneously reducing endothelial nitric oxide (eNO) generation and its half-life." (PMID 28824543, 2017). "Despite such a significant contribution of IL-6 and TNF-α to endothelial dysfunction a knowledge gap investigating how IL-6 and TNF-α affect each other in endothelial cell in T2D still exists." (PMID 29095915, 2017). "It appears to be the first study to find that a reciprocal inhibitory regulation between TNF-α and IL-6 is responsible for endothelial dysfunction in T2D." (PMID 29095915, 2017). "Nevertheless, we observed that nmMLCK is involved in IL-6 release which is known to induce endothelial dysfunction." (PMID 29057883, 2017). "The increase in immune cells to the vascular wall serves to further promote endothelial dysfunction and recruitment of IL-6 and superoxide producing cells, such as neutrophils and macrophages." (PMID 29186034, 2017). "Inflammatory biomarkers (Il-6 and TNFα) and an endothelial dysfunction biomarker (ET-1) showed significantly higher levels in T2DM-CKD, and a positive correlation with TMAO in the T2DM-CKD patients." (PMID 28925931, 2017). "IL-6 has been linked with CV disease and, together with VCAM-1, has been implicated in in-vitro and animal models of endothelial dysfunction in uraemia." (PMID 28829810, 2017). "IL-6 signaling mediates a vast array of effects in the vascular wall, including endothelial activation, vascular permeability, immune cell recruitment, endothelial dysfunction, as well as vascular hypertrophy and fibrosis." (PMID 29186034, 2017). "The depletion of IL-6 signaling protected against angiotensin II-induced NO-mediated endothelial dysfunction in mouse carotid artery." (PMID 29095915, 2017). "It is increasingly recognized that inflammatory cytokines, such as interleukin-6 (IL-6), contribute to endothelial dysfunction and vascular hypertrophy and fibrosis." (PMID 29186034, 2017). "Our findings show that direct exposure of TEMPOL, an O2- scavenger, to vessels from diabetic mice reverses endothelial dysfunction, which is similar to the levels observed in the db/db+anti-IL-6 mice." (PMID 29095915, 2017). "The two inflammatory markers TNFα and IL-6, and the endothelial dysfunction marker ET-1 showed a significant difference in the two groups, p < 0.05." (PMID 28925931, 2017). "The results of this study provide evidence that either IL-6 inhibition or TNF deficiency has an interactive down-regulatory action on the other in type 2 diabetic coronary arterioles and it contributes to the endothelial dysfunction." (PMID 29095915, 2017). "MS is associated with increased circulating levels of proinflammatory cytokines such as interleukin-6 (IL-6) and decreased anti-inflammatory factors such as adiponectin, which are both able to influence insulin sensitivity and endothelial dysfunction." (PMID 28163257, 2017).
endothelial dysfunction (continued). "The interaction of TNF-α and IL-6 appears to have a pivotal role in T2D-induced endothelial dysfunction in coronary microcirculation." (PMID 29095915, 2017). "The present studies, therefore, strongly suggests that IL-6 is an important contributor of T2D-mediated endothelial dysfunction, especially through elevated O2- production and attenuated SOD2 protein expression." (PMID 29095915, 2017). "The same study also showed that placental IL6 expression was much lower in early-onset PE, and suggested that the increase in serum IL6 was more likely resulted from maternal endothelial dysfunction than a direct consequences of defective placenta." (PMID 27780539, 2016). "Elevated concentrations of interleukin-6 (IL-6), tumor necrosis factor (TNF-α) and other inflammatory cytokines in plasma have been shown to be linked to endothelial dysfunction in obese patients." (PMID 27250532, 2016). "Significant correlations were found between plasma dp-ucMGP levels and markers for low-grade inflammation (IL-6) and endothelial dysfunction (VCAM and von Willebrand factor)." (PMID 26495126, 2015). "We decided to study the effect of several cytokines involved in the inflammatory process, such as TNF-α, IL-6 and IL-1β on some markers of endothelial dysfunction and activation in ECs and the possible protective effect of the oleate against those stimuli." (PMID 26055507, 2015). "IL-6 is a pleiotropic cytokine that has a role not only in the acute phase response but also in chronic inflammation and endothelial dysfunction." (PMID 25938443, 2015). "It is reported that IL-6, IL-8 and sICAM-1 are closely related to endothelial dysfunction, which subsequently results in the progression of vascular dysfunction." (PMID 25887435, 2015). "The ABIN(D485N) mice display endothelial dysfunction and cardiac hypertrophy, which is possibly mediated through IL-6 and, to a lesser degree, IL-1α." (PMID 25648164, 2015). "STAT3 activation has been shown to have a number of effects, including inhibition of eNOS promoter activity and reductions in eNOS gene expression, thereby providing a mechanistic link by which IL-6 serves to produce endothelial dysfunction." (PMID 25400581, 2014). "IL-6 not only promotes endothelial dysfunction but also affects human osteoblast differentiation, thus contributing to osteopenia." (PMID 25210716, 2014). "Our data also demonstrate along with increases in arterial pressure that there is a strong correlation between increases in IL-6 and vascular macrophage accumulation and the degree of endothelial dysfunction produced by Ang II." (PMID 25400581, 2014). "Overall, our findings provide direct evidence that IL-10 plays a major role to suppress age-induced oxidative stress, increases in IL-6 expression, and endothelial dysfunction." (PMID 24400151, 2013). "The inhibition of tectorigenin on TNF-α and IL-6 production was, at least in part, responsible for its amelioration of endothelial dysfunction." (PMID 23840461, 2013). "Endothelial dysfunction in response to angiotensin II requires expression of both IL-6 and the Nox2 component of NADPH oxidase." (PMID 24400151, 2013). "Our findings suggest a novel role for IL-10 to protect against age-related increases in expression of IL-6, oxidative stress, and endothelial dysfunction." (PMID 24400151, 2013). "Interleukin-6 is involved in atherogenesis and plaque destabilization through increased inflammatory stress, endothelial dysfunction, and local enhancement of thrombosis." (PMID 23028694, 2012). "With our report, VEGFA rivals IL6 as the most replicated ALI genetic risk factor, and focuses attention on the critical contribution of endothelial dysfunction to the development of ALI." (PMID 22742663, 2012). "The pro-inflammatory cytokine IL-6 is reported to promote endothelial dysfunction, smooth muscle cell proliferation and migration as well as recruitment and activation of inflammatory cells." (PMID 22022523, 2011).
endothelial dysfunction (continued). "In particular, visceral fat contributes to inflammation and endothelial dysfunction through secretion of adipokines, like TNFα or IL-6, which are secreted by the lipid tissue after macrophage recruitment (through monocyte chemoattractant protein-1 (MCP-1)." (PMID 21808640, 2011). "For example, our previous studies have shown that IL‐6 can induce endothelial dysfunction." (PMID 41532698, 2026). "Gene expression of MMP-2 and MMP-9 in peripheral blood leukocytes and circulating levels of MMP-2, MMP-9, pro-inflammatory cytokines (TNF-α, IL-6), and endothelial dysfunction markers (Endothelin-1 [ET-1], adhesion molecules) were quantified via qRT-PCR and ELISA." (PMID 41598609, 2026). "Also, elevated plasma IL-6 levels were detected in Ang II-triggered endothelial dysfunction and pressure overload." (PMID 41592077, 2026). "Endothelial dysfunction and hemodynamic disturbances in regions of turbulent blood flow promote the expression of adhesion molecules and local inflammatory cytokines, such as IL-6 and IL-8." (PMID 40429463, 2025). "Furthermore, inflammation contributes to preeclampsia progression, as elevated levels of tumor necrosis factor-alpha (TNF-α) and interleukin-6 (IL-6) promote immune dysregulation, exacerbate vascular inflammation, and increase endothelial dysfunction." (PMID 40218901, 2025). "Additionally, inflammation, marked by elevated cytokines like tumor necrosis factor-alpha (TNF-α) and interleukin-6 (IL-6), contributes to myocardial injury and endothelial dysfunction." (PMID 40313442, 2025). "Our in vitro experiments suggest that IL-6 trans-signaling may be the dominant driver of endothelial dysfunction in this context." (PMID 41417254, 2025). "The onset and worsening of endothelial dysfunction are associated with increased levels of inflammatory markers and mediators, including CRP, intercellular and vascular cell adhesion molecules, fibrinogen, interleukin (IL) 1b, and IL-6." (PMID 38965367, 2025). "While a direct causal relationship between IL-6 and adverse post-CEA outcomes has not yet been established, accumulating mechanistic and longitudinal evidence indicates that IL-6 plays a pathophysiologically central role in vascular inflammation, endothelial dysfunction, and plaque instability." (PMID 41440557, 2025). "This shift from Th1 to Th2 immunity might exacerbate plasma leakage and organ damage through endothelial dysfunction mediated by Il6 and Il8, thereby promoting the progression of severe dengue manifestations, such as DHF and DSS." (PMID 40623122, 2025). "Other studies suggest that pro-inflammatory mediators, such as TNF-α, IL-6, and IL-8, enter the circulation and create a systemic inflammatory environment, which may lead to endothelial dysfunction and exacerbate pain." (PMID 40771919, 2025). "UFP-induced ROS lead to activation of MAPKs through induced phosphorylation of p38 and ERK1/2 MAPKs that may further result in endothelial dysfunction through production of cytokines such as IL-6." (PMID 40283676, 2025). "IL-6, more than TNF-α, may drive endothelial dysfunction and altered vascular reactivity associated with postoperative hypertension." (PMID 41010423, 2025). "Biomarkers of inflammation (IL-6) and endothelial dysfunction (ADMA) provide complementary prognostic information and could be considered for integration into future risk stratification models." (PMID 41450363, 2025). "Chronic activation of the immune system results in the production of proinflammatory cytokines, such as interleukin-6 (IL-6), tumor necrosis factor-alpha (TNF-α), and C-reactive protein (CRP), which are central to the inflammatory cascade associated with endothelial dysfunction and vascular damage." (PMID 40787484, 2025).
endothelial dysfunction (continued). "Adipose tissue, particularly visceral fat, becomes dysfunctional and secretes pro-inflammatory cytokines, including tumor necrosis factor-alpha (TNF-α), interleukin-6 (IL-6), and resistin, which promote hepatic fat accumulation, endothelial dysfunction, and vascular inflammation." (PMID 41020888, 2025). "This study demonstrates significant endothelial dysfunction and elevated levels of inflammatory cytokines, particularly IL-6 and TNF-α, in patients with acute coronary syndrome (ACS) compared to those with stable coronary artery disease (CAD) or chest pain of non-epicardial CAD ischemic origin." (PMID 40310443, 2025). "Elevated levels of pro-inflammatory cytokines, such as tumour necrosis factor-alpha (TNF-alpha), interleukin-1 (IL-1), and interleukin-6 (IL-6), contribute to endothelial dysfunction by reducing the bioavailability of nitric oxide, increasing oxidative stress, and impairing vasodilation." (PMID 40958238, 2025). "At the molecular level, there is a significant increase in pro-inflammatory cytokines and angiogenic growth factors, including vascular endothelial growth factor (VEGF) and interleukin-6 (IL-6), which contribute to endothelial dysfunction and the progression of coagulopathy." (PMID 40255784, 2025). "Consistent with these hematologic abnormalities, hyperglycemic patients showed significantly higher levels of ESR, CRP, ferritin, and fibrinogen, suggesting a pronounced proinflammatory milieu driven by oxidative stress, endothelial dysfunction, and activation of the IL-6/TNF-α cytokine axis." (PMID 41156159, 2025). "Smoking promotes CAS via C-reactive protein-induced IL-6 expression, nicotine activation of α7-nicotinic acetylcholine receptors, adrenergic stimulation, catecholamine release, endothelial dysfunction, oxidative stress, platelet activation, and increased blood viscosity." (PMID 41464622, 2025). "In SLE patients, particularly those with high disease activity, significant endothelial dysfunction may occur, which is likely linked to elevated SLEDAI scores and increased levels of proinflammatory cytokines such as TNF-α, IL-1, IL-6, and interferon (IFN)-α." (PMID 41204247, 2025). "Studies examining specific pathways, such as IL-6’s role in endothelial dysfunction, could also uncover new therapeutic targets." (PMID 40363978, 2025). "Additionally, interleukin signaling pathways involving cytokines like IL-6 and IL-8 contribute to systemic inflammation and endothelial dysfunction, worsening PE outcomes." (PMID 39996749, 2025). "Emerging therapies, such as monoclonal antibodies targeting pro-inflammatory cytokines like IL-6, may also offer novel avenues for addressing inflammation-driven endothelial dysfunction." (PMID 40143236, 2025). "Empirical evidence suggests that both short and long sleep durations are associated with elevated levels of inflammatory markers, such as C-reactive protein (CRP) and interleukin-6 (IL-6), which contribute to endothelial dysfunction and arterial plaque formation." (PMID 40391016, 2025). "Additionally, inflammatory mediators, including TNF-α and IL-6, are upregulated, contributing to endothelial dysfunction and hepatocellular apoptosis." (PMID 40005408, 2025). "Additionally, further investigation should measure oxidative stress and additional measurements for inflammatory biomarkers such as IL6, which is considered a prominent mediator of sleep disturbances, physical inactivity, and endothelial dysfunction." (PMID 39871651, 2025). "It is worth mentioning the central cytokines that play a role in the establishment of CVD, specifically interleukin-6 (IL-6) and interleukin-1β (IL-1β), which contribute to the progression of the atherosclerotic process by promoting endothelial dysfunction and plaque instability." (PMID 40284036, 2025).
endothelial dysfunction (continued). "Tumour necrosis factor-alpha (TNF-α) and interleukin-1 beta (IL-1β) have been shown to play integral parts in systemic inflammation and endothelial dysfunction, while interleukin-6 (IL-6) and interleukin-8 (IL-8) have been demonstrated to contribute to vascular resistance and thrombosis." (PMID 41439053, 2025). "This activation leads to the rapid release of cytokines such as tumor necrosis factor-alpha (TNF-α), interleukin-1 beta (IL-1β), interleukin-6 (IL-6), and interleukin-18 (IL-18), driving systemic inflammation and leading to endothelial dysfunction, tissue damage, and increased vascular permeability." (PMID 39594987, 2024). "The SARS-CoV-2 genome encodes 29 proteins that, when cloned and overexpressed, significantly decrease endothelial permeability tight junction proteins and increase von Willebrand factor expression and interleukin-6 (IL-6) levels, indicating endothelial dysfunction." (PMID 40276305, 2024). "Additionally, IL-6 contributes to endothelial dysfunction, the initial step in vascular injury and atherosclerotic plaque evolution, and it also promotes inflammation." (PMID 39683498, 2024). "Soluble HIV gp120 has been reported to induce apoptosis in endothelial cells of coronary vessels via the co-receptor CXCR4, induce endothelial permeability leading to endothelial dysfunction and induction of pro-inflammatory cytokines IL-6 and IL-8 in endothelial cells." (PMID 39081863, 2024). "Moreover, IL-6 can promote endothelial dysfunction and stimulate endothelial cell-secreted endothelial microparticles to induce endothelial dysfunction and inhibit angiogenesis." (PMID 38195507, 2024). "These inflammatory and endothelial dysfunction markers include IL-6, IL-8, ICAM and VCAM." (PMID 38961103, 2024). "Mental disorders may enhance the expression of pro-inflammatory cytokines, such as interleukin-6 (IL-6) and tumor necrosis factor-alpha (TNF-ɑ), which are associated with endothelial dysfunction and metabolic alterations." (PMID 38469409, 2024). "Additionally, an imbalance in cytokine production, with elevated levels of pro-inflammatory cytokines such as TNF-α and IL-6 and reduced levels of anti-inflammatory cytokines, contributes to endothelial dysfunction and impaired placentation." (PMID 39062815, 2024). "Endothelial dysfunction may contribute to the accumulation of leukocytes and the induction of tissue damage, as well as the further release of cytokines (IL-6, IL-1B, and TNF-alpha)." (PMID 39598310, 2024). "In our study, the result of correlation coefficient of inflammatory markers (IL-6, IL-8) and endothelial dysfunction marker (ICAM, VCAM) with coagulation markers (PT, aPTT) of overall (IL-6, IL-8, ICAM, VCAM × PT, APTT) had a statistical significantly positive correlation." (PMID 38961103, 2024). "Finally, the expression of miR-148a-3p and SIRT7 protein levels on the inflammatory state induced by IL-6 was then evaluated, given their emerging role during endothelial dysfunction." (PMID 38791128, 2024). "One possible explanation is that the systemic inflammatory response accompanying asthma exacerbations leads to endothelial dysfunction and smooth muscle contraction in the blood vessels through the release of various inflammatory mediators, such as interleukin-6 and leukotrienes." (PMID 38918763, 2024). "TNF-α and IL-6 are involved in the appearance of endothelial dysfunction." (PMID 37762225, 2023). "Moreover, this study investigated the contribution of only some cytokines (TNF-α, IL-6) in the development of endothelial dysfunction, but a much higher number of cytokines are increased in pSS." (PMID 37762225, 2023). "Interestingly, the activation of monocytes is stimulated by endothelial dysfunction probably due to Ang-II induced ROS generation and IL-6 release and also due to monocyte STAT activation." (PMID 37854465, 2023).